TRPA1 (transient receptor potential cation channel subfamily A member 1)
Diseases named in the same sentence as TRPA1 in open-access papers (continued):
Sharing a sentence is not in itself a finding about the gene and the disease.
migraine (continued). "Inhibition ROS and deactivation of TRPA1 channels may have therapeutic benefits in preventing stress-triggered migraine via CGRP." (PMID 30841847, 2019). "Our data suggest that reduction of ROS production and blockade of TRPA1 may provide alternative therapeutic benefits to CGRP in preventing migraine." (PMID 30841847, 2019). "It is reasonable to propose that ROS is required for TRPA1 signaling in migraine progression." (PMID 30841847, 2019). "The TRPV1 and TRPA1 channels play a critical role in migraine pathophysiology." (PMID 31885641, 2019). "The results of these studies suggest that compounds capable of desensitizing TRPA1 and TRPA1-expressing nerve endings may be viable new therapeutics for migraine." (PMID 30970581, 2019). "We further examined whether ROS and TRPA1 activation would produce similar effects on preventing the reduced cortical susceptibility to CSD by inhibition of CGRP, a known target for migraine prevention." (PMID 30841847, 2019). "Based on these findings, it was proposed that reducing ROS production together with blockade of neuronal TRPA1 could help prevent stress-triggered migraine." (PMID 31336748, 2019). "It still remains to be studied whether migraine patients and/or infants suffering from colic pain have a hypermethylated TRPA1 promoter and increased TRPA1 expression." (PMID 30388732, 2018). "Furthermore, these results highlight TRPA1 as a potential target for the development of new migraine treatments." (PMID 30238173, 2018). "Taking into account that TRPA1 is co-localized in a subpopulation of TRPV1-expressing neurons, this result supports the hypothesis that meningeal TRPA1 may also contribute to migraine pain." (PMID 30388732, 2018). "Interestingly, some chemical agents such as cigarette smoke, ammonia, formaldehyde, and chlorine can induce migraine attacks—all these compounds are TRPA1 agonists." (PMID 30155469, 2018). "Another member of gasotransmitter family that presumably has a role in migraine, hydrogen sulfide, was shown to activate nociceptive trigeminal neurons partly due to action on TRPA1 potentially providing one more migraine mechanism involving TRPA1." (PMID 30388732, 2018). "Compelling evidence supports the proposal that TRPA1 antagonists may provide a promising future alternative for the prevention and acute treatment of migraine." (PMID 30388732, 2018). "In addition, TRPA1 agonists cause the activation of second order neurons in the trigeminal nucleus caudalis (TNC), suggesting their role in the initiation of migraine attacks." (PMID 28884307, 2017). "Thus, the involvement of TRPA1 is emerging as a major contributing pathway in migraine, though studies on the importance of this TRP channel in the pathophysiology of migraine, and in particular in the trigeminal hyperalgesia, are still limited." (PMID 28884307, 2017). "The thermo-TRP ankyrin type-1 (TRPA1) channels - sensors of oxidative, nitrative and electrophilic stress – have been involved in different models of pain diseases and seem to play a key role also in the mechanisms of migraine pain." (PMID 28884307, 2017). "In other words, TRPA1 is the bridge between oxidative stress and neuroinflammation in migraine." (PMID 28775706, 2017). "Moreover, activation of TRPA1 degranulates mast cells to release histamine and serotonin – all of which are key components of migraine pathophysiology." (PMID 28091820, 2017). "TRPA1 and TRPV1 have also been involved in the development of migraine, which can be activated by a number of TRPA1 agonists and might be attenuated by repeated desensitizing administration of capsaicin to the nasal mucosa." (PMID 28649203, 2017). "Both in humans and animals, NO directly activates TRPA1 via S-nitrosylation, and therefore, could serve as a mechanism for trigeminal excitation and migraine." (PMID 27854251, 2016). "Many common triggers of migraine act as TRPA1 agonists, thereby inducing the release of CGRP." (PMID 26184313, 2015).
migraine (continued). "Additionally, TRPA1 activation may contribute to oxidative stress, a potential factor in migraine pathogenesis." (PMID 40391079, 2025). "TRPA1 localizes in the perivascular meninges on nociceptive nerve endings and may sensitize meningeal nociceptors, and second-order trigeminal neurons, which may be important in migraine." (PMID 39064963, 2024). "In summary, TRPA1 may connect oxidative stress with pain induction and transmission in migraine." (PMID 39064963, 2024). "Additionally, changes in cerebral blood flow are observed when migraines occur, and TRPA1 has been hypothesized to contribute to the regulation of these changes in cerebral blood flow." (PMID 39273183, 2024). "Also, TRPA1 may be important in the mechanisms of action of BoNTA, an effective drug in the prevention of chronic and high frequency, episodic migraine." (PMID 37326902, 2023). "Therefore, epigenetic regulation of TRPA1 may play a role in efficacy and safety of anti-migraine therapies targeting TRP channels and CGRP." (PMID 37326902, 2023). "Therefore, epigenetic regulation of TRPA1 in IBD may have some common pathways with its counterpart in migraine." (PMID 37326902, 2023). "Additionally, notwithstanding the great amount of available literature supporting our findings about TRPA1 involvement in migraine, our data may benefit from validation with different TRPA1 antagonists." (PMID 36430567, 2022). "However, TRPA1-invovled signaling events in migraine are poorly understood." (PMID 34488620, 2021). "Dysregulated calcium currents as seen in the context of migraine derive largely from aberrant function of the high-voltage activated calcium channel CaV2.1 and the transient receptor potential ankyrin channel, encoded by the genes CACNA1A and TRPA1, respectively." (PMID 33799975, 2021). "Therefore, we propose that the TRPA1/PKA/SFKs pathway may exist to play a regulatory role in migraine pathogenesis, possibly involving interaction with NMDA receptors." (PMID 34830154, 2021). "Notably, CGRP receptor antagonists block the TRPA1 agonists-enhanced meningeal blood flow, indicating TRPA1-mediated migraine-like symptoms might be dependent on CGRP." (PMID 34830154, 2021). "In addition, TRPA1 not only mediates oxidative stress in TG and nociceptive behaviors in a migraine model induced by NO donors, but also plays a central role in modulating cortical neuronal activity and cortical susceptibility to CSD, the latter of which also involves CGRP." (PMID 34830154, 2021). "However, TRPA1-induced signaling in migraine pathogenesis is poorly understood." (PMID 34830154, 2021). "The TRPA1 activation and ensuing oxidative stress may sensitize the meningeal nociceptors and the second order trigeminal neurons to show periorbital allodynia, which might be relevant to glyceryl trinitrate-evoked migraine-like headaches in humans." (PMID 31612077, 2019). "This also led to several subsequent studies examining TRPA1-desensitizing compounds such as parthenolide from the feverfew herb and isopetasin from butterbur for their ability to desensitize meningeal nociceptors, potentially explaining the efficacy of these herbs in the treatment of migraine." (PMID 30970581, 2019). "Therefore, the inhibition of ROS and deactivation of TRPA1 channels may have a synergistic therapeutic benefit in preventing stress-triggered migraine via CGRP by a central mechanism." (PMID 31835593, 2019). "Additionally, the finding that a wide diversity of chemical compounds are TRPA1 agonists is in line with the proposal that TRPA1 in trigeminal neurons may be a common mechanism for a wide variety of migraine triggers." (PMID 30388732, 2018). "In this regard, TRPA1 may represent a novel target for treating migraine." (PMID 29430557, 2017).
migraine (continued). "Cortical spreading depression, which is considered to be a mechanism for migraine aura, appears to be associated with increased levels of reactive oxygen species and LPO products, and their interactions with TRPA1 and the resulting CGRP release may exacerbate migraine pathology." (PMID 25233127, 2014). "Thus, TRP channels, and particularly TRPA1, may be proposed as novel pathways in migraine pathophysiology and as possible new targets for its treatment." (PMID 23941062, 2013). "In particular, activated TRPA1, TRPM2, TRPM8, and TRPV1 channels participate in migraine progress through amplifying neuroinflammation." (PMID 41399206, 2025). "While H2S interacts with NO to form HNO, a potent TRPA1 activator leading to CGRP release and migraine onset, it also exhibits neuroprotective properties by reducing oxidative stress and neuroinflammation via Nrf2 activation." (PMID 40391079, 2025). "Agonists of TRPA1 induced the release of CGRP, neurogenic inflammation, pain sensitivity, and behaviors typical for migraine in experimental animals." (PMID 39064963, 2024). "Stimulating transient receptor potential (TRP) channels, such as ankyrin 1 (TRPA1), induces CGRP release and migraine attacks." (PMID 39457613, 2024). "Among the TRP channels, TRPV1, TRPA1, and TRPM8 have been well studied and are being investigated as potential therapeutic targets for migraine prevention and treatment." (PMID 37175602, 2023). "Transient receptor potential cation channel subfamily A member 1 (TRPA1), a member of the TRP channels superfamily, is activated by many migraine triggers and expressed in trigeminal neurons and brain regions that are important in migraine pathogenesis." (PMID 37326902, 2023). "TRPV1 and TRPA1 potentially play a role with CGRP in headaches and are also involved in sensitivity to environmental factors such as heat, pH changes, and natural migraine triggers." (PMID 36831105, 2023). "Such physical interactions between two receptors can alter the receptor properties and excitability, so the cooperation of TRPA1 and TRPV1 should be carefully considered in chronic pain-related disease, such as in migraine, studies." (PMID 36982450, 2023). "In addition, TRPA1 may activate oxidative stress by inducing the occurrence of intracellular Ca2+ overload, resulting in increased release of intracellular inflammatory factors, neuroinflammation, and migraine." (PMID 37039840, 2023). "Capsaicin and ethanol are known to release the pro-migraine neuropeptide, CGRP, from terminals of TRPV1+ve and TRPA1+ve DRG neurons." (PMID 37101198, 2023). "TRPA1 activation by isothiocyanates is followed by strong desensitisation; self- and cross-desensitisation of TRPA1 and TRP subfamily vanilloid member 1 (TRPV1), seems to be relevant to the anti-migraine properties of some analgesics." (PMID 36674850, 2023). "In particular, the subtypes ankyrin 1 (TRPA1) and vanilloid 1 (TRPV1) are activated by migraine provoking agents." (PMID 35350752, 2022). "TRPA1 and TRPM8 are transient receptor potential channels expressed in trigeminal neurons that are related to pathophysiology in migraine models." (PMID 36272975, 2022). "The transient receptor potential ankyrin 1 (TRPA1) channels may play a role in this multifaceted scenario, as suggested by evidence provided by our group and other researchers showing that TRPA1 antagonism is indeed effective for abolishing migraine-like changes in preclinical models." (PMID 36430567, 2022). "At the neuronal level, i.e., on the trigeminal nociceptors, TRPA1 activation promotes the release of the neuropeptide CGRP, thus starting the cascade of molecular mechanisms that lead to neurogenic inflammation and migraine pain." (PMID 36430567, 2022). "Considering that TRPA1 is involved in headache and migraine mechanisms, we aimed to investigate the development of PMA in a PMS-EAE mouse model and we also intended to evaluate the involvement of TRPA1." (PMID 34451927, 2021).
migraine (continued). "Coincidently, we recently show that TRPA1 plays a key role in mediating CSD in the mouse brain slice, suggesting TRPA1 as a drug target for preventing migraine aura." (PMID 30841847, 2019). "TRPA1 is also co-expressed in CGRP-positive nociceptors and has attracted significant attention in the context of migraine pathophysiology due to its sensitivity to numerous exogenous and endogenous compounds." (PMID 31336748, 2019). "The transient receptor potential ankyrin A 1 (TRPA1) channel and calcitonin gene-related peptide (CGRP) are targets for migraine prophylaxis." (PMID 30841847, 2019). "Considering that TRPA1 channels are sensitive to oxidative stress, reactive oxygen species (ROS) have been recently proposed as an activator of central TRPA1 channels, triggering the release of CGRP and consequently the development of migraines." (PMID 31835593, 2019). "The expression levels of the genes coding for c-Fos, TRPA1, calcitonin gene-related peptide (CGRP) and substance P (SP) in peripheral and central areas relevant for migraine pain were analyzed." (PMID 28884307, 2017). "Again, recent development of TRPA1 and TRPM8 antagonists for pain conditions is likely to promote testing of these drugs in clinical trials for specific migraine and headache conditions." (PMID 27854251, 2016). "Although there is no specific information on the role of these channels to peripheral nociceptor sensitization or central sensitization in migraine, it is possible that TRP channels, and in particular TRPV1 and TRPA1, contribute to this key mechanism." (PMID 23941062, 2013). "TRPA1 channels, activated by oxidative stress products, depolarize TG neurons, thereby evoking CGRP release and neurogenic inflammation that ultimately precipitate migraine attacks." (PMID 41399206, 2025). "Pyrazolone derivatives, such as propyphenazone and dipyrone, selectively inhibit TRPA1, thereby alleviating migraines independent of prostaglandin production." (PMID 39273183, 2024). "TRPA1 was identified as a sensor of RONS at the sites of inflammation or tissue damage in several disorders, including inflammatory and neuropathic pain and migraine." (PMID 39064963, 2024). "Additionally, SFKs serve as a convergent hub by transmitting signaling of NR2A-containing receptor and purinergic P2X receptor 7 in cortical spreading depression migraine model and that of TRPA1 and CGRP signaling in ex vivo models of migraine." (PMID 39390364, 2024). "Considering the importance of intracranial sensitization in the pathomechanism of migraine, the functional sensitization of TRPA1, TRPV1, and other TRP receptors involved in intracranial pain sensation at the receptor level should be discussed as a provocative factor in migraine attacks." (PMID 36982450, 2023). "Extensive preclinical studies focusing on TRP ion channels have concluded that TRPA-1 and TRPV-1 could play crucial roles in the activation of several substances (as migraine triggers) that evoke migraine pain." (PMID 36835524, 2023). "Parthenolide, another herb extract, is a partial TRPA1 agonist and has the ability to desensitize it, effecting anti-migraine responses on CGRP-mediated trigeminal activity, and positioning it as a potential migraine target." (PMID 37370051, 2023). "For instance, TRPA1 and TRPV1 might be involved in migraine, headache and dental pain, for which TMD shares significant co-morbidity." (PMID 37033371, 2023). "Reactive oxygen species (ROS), which are also involved in the pathomechanism of migraine and may mediate CSD, can activate TRPA1." (PMID 36614146, 2022). "There might be a positive loop between TRPA1 activation and CGRP release in migraine pathogenesis, but which needs clarification." (PMID 34830154, 2021). "TRPA1 channels expressed in the central nervous system (CNS) have a critical role in the modulation of cortical spreading depression (CSD), which is a key pathophysiological basis of migraine pain." (PMID 31835593, 2019).
migraine (continued). "Therefore, we suggest that auricular ES pretreatment is beneficial for the treatment of migraine and this effect is partly related to CGRP/COX-2/TRPV1/TRPA1 signaling pathways." (PMID 31885641, 2019). "More recent work from these authors has shown that repeated exposure to acrolein potentiates meningeal vasodilatory responses to TRPA1 and TRPV1 activation and leads to migraine-like cutaneous hypersensitivity and increased responses of the trigeminal afferent system to touch." (PMID 30970581, 2019). "Besides capsaicin, other TRP channel agonists have been described as migraine triggers, thereby placing TRPV1, TRPA1, and TRPM8 in the therapeutic spotlight for the development of migraine treatments." (PMID 30155469, 2018). "Indeed, in Drosophila brain, DH31 secretion is controlled by TRPA1 to promote awakening, and in mammals CGRP release is induced by TRPA1, for example, to control blood flow and blood pressure, and induces migraines." (PMID 30180210, 2018). "For example, TRPM8 was strongly linked to migraine in a human genome-wide association study, while genome-wide studies have not revealed such a link between TRPA1 and migraine." (PMID 30388732, 2018). "Activation of TRPV1 and TRPA1 on meningeal nerve endings induces the release of vasoactive neuropeptides CGRP and substance P and contributes to different forms of headache including migraine." (PMID 28798669, 2017). "The TRPA1–CGRP interaction may be the key activity of TRPA1 related to migraine pain, as the involvement of CGRP released from the terminals of trigeminal neurons in migraine-related neurogenic inflammation may belong to the main mechanisms of migraine headaches." (PMID 39064963, 2024). "It is suspected that while TRPA1 channels may play a role in migraine pain, it does not directly activate nociceptors in the meninges to cause migraine and only has a modulatory role." (PMID 38481473, 2024). "Activation of TRPA1 by agonists may lead to the release of neuropeptides, including CGRP and substance P (SP) that may generate neurogenic inflammation, an important aspect of migraine pathogenesis." (PMID 37326902, 2023). "As PKA activation promotes CGRP release but not increases in IL-1β gene expression, we therefore propose that PKA may direct SFKs to mediate CGRP release but not IL-1β gene expression downstream TRPA1 in migraine." (PMID 34830154, 2021). "A number of these channels, including transient receptor potential cation channel subfamily A, member 1 (TRPA1); subfamily V, member 1 (TRPV1), subfamily V, member 4 (TRPV4), and subfamily M, member 8 (TRPM8) are highly expressed in primary sensory neurons and play a role in migraine." (PMID 34790097, 2021). "In recent years, our group has developed a family of lipoic acid-based TRPA1 antagonists named ADM, which are able to revert not only oxaliplatin-induced neuropathic pain but also inflammatory trigeminal allodynia, which is particularly relevant in the treatment of orofacial pain and migraine pain." (PMID 31835593, 2019). "On a molecular basis, the TRPA1 (Transient receptor potential ankyrin subtype 1) ion channels in nociceptors allow the release of calcitonin gene-related peptide (CGRP) from dural afferents upon activation, mediating neurogenic inflammation, and migraine behavioral picture in animal models." (PMID 28775706, 2017). "In conclusion, the therapeutic effectiveness of BoNT-A in migraine prevention may be explained by the simultaneous lowering of CGRP release, sensitivity to molecules that activate nociceptive meningeal C-afferents via TRPV1 and TRPA1, and pre-existing inflammation." (PMID 36668895, 2023). "However, TRPA1 antagonists have not been specifically tested for migraine so far although a series of high affinity and selective TRPA1 antagonists are currently undergoing phase I and phase II clinical trials for various diseases characterized by pain component." (PMID 37569648, 2023).